TSTD2 (thiosulfate sulfurtransferase like domain containing 2)
Synonyms: C9orf97; PP4189
Tractability: PROTAC: ubiquitination databases record sites on it.
Gene: Protein-coding gene on chromosome 9 (97,600,080 to 97,633,377, reverse strand). Ensembl gene ENSG00000136925.
Subcellular location (Human Protein Atlas): Nucleoplasm
Gene Ontology:
Molecular function: protein binding
Genetic constraint (gnomAD): Loss-of-function variants: 30 observed, 39.77 expected, observed/expected ratio (o/e) 0.75, 90% interval 0.56 to 1.02. The upper end of that interval is the gene's LOEUF score, 1.02, which puts it in group 4 of 6, group 1 being the genes least tolerant of losing a copy. Missense variants: 505 observed, 549.09 expected, observed/expected ratio (o/e) 0.92, 90% interval 0.85 to 0.99. Synonymous variants: 171 observed, 193.56 expected, observed/expected ratio (o/e) 0.88, 90% interval 0.78 to 1.
Homologues: Orthologues: chimpanzee TSTD2 (99% identical), macaque TSTD2 (95% identical), dog TSTD2 (86% identical), pig TSTD2 (85% identical), rabbit TSTD2 (83% identical), guinea pig TSTD2 (80% identical), mouse Tstd2 (77% identical), rat Tstd2 (67% identical), tropical clawed frog tstd2 (56% identical).
Diseases named in the same sentence as TSTD2 in open-access papers:
TSTD2 is named in the same sentence as 14 diseases in open-access papers, as found by Europe PMC text mining. Sharing a sentence is not in itself a finding about the gene and the disease. The quoted sentences say what the papers report.
atherosclerosis (1 paper, 2022). A disease characterized by the build-up of fatty material and calcium deposition in the arterial wall resulting in partial or complete occlusion of the arterial lumen. "Furthermore, Spearman's rank correlation analysis revealed TSTD2-Ab levels to be strongly associated with measures of atherosclerosis severity, including plaque scores, intima-media thickness of the carotid artery and the cardio-ankle vascular index." (PMID 36699658, 2022). "If TSTD2 plays a causal role in the regulation of hypertension, it may be used as a therapeutic target to prevent the development of atherosclerosis." (PMID 36699658, 2022). "Thus, the TSTD2 antibody may predominantly reflect the development of atherosclerosis, and may thus be associated with the presence of aCI and CKD." (PMID 36699658, 2022). "Using ProtoArray® screening of samples from patients with atherosclerosis, the present study identified thiosulfate sulfurtransferase-like domain-containing 2 (TSTD2) as a novel atherosclerosis antigen." (PMID 36699658, 2022). "The present study examines the use of the anti-thiosulfate sulfurtransferase-like domain-containing 2 (TSTD2) autoantibody as a novel biomarker for atherosclerosis-related cerebral infarction and CKD in the sera of patients with atherosclerosis." (PMID 36699658, 2022). "The present study identified the TSTD2 antibody as a novel biomarker that may be used for the detection of atherosclerosis-related aCI and CKD." (PMID 36699658, 2022). "Therefore, the present study performed ProtoArray® screening and identified a novel autoantibody marker and selected the TSTD2 autoantibody as a candidate marker for atherosclerosis." (PMID 36699658, 2022). "Thus, TSTD2-Abs may thus be a promising novel biomarker for atherosclerosis-related cerebral infarction and kidney disease." (PMID 36699658, 2022).
Camptodactyly (1 paper, 2025). The distal interphalangeal joint and/or the proximal interphalangeal joint of the fingers or toes cannot be extended to 180 degrees by either active or passive extension. "Interestingly, one of our replicated association genes in inhibitory neurons, TSTD2, is also implicated in a rare hearing‐loss disorder called camptodactyly‐tall stature‐scoliosis‐hearing loss syndrome." (PMID 41457042, 2025).
chronic kidney disease (1 paper, 2022). Impairment of the renal function secondary to chronic kidney damage persisting for three or more months. "This demonstrated the levels of TSTD2 antibodies (TSTD2-Abs) to be significantly higher in patients with acute cerebral infarction or chronic kidney disease than in healthy donors." (PMID 36699658, 2022).
diabetes mellitus (1 paper, 2022). A metabolic disorder characterized by abnormally high blood sugar levels due to diminished production of insulin or insulin resistance/desensitization. "Spearman's correlation analysis revealed that blood sugar, a typical diabetes mellitus (DM) marker, was related to the serum TSTD2 antibody levels." (PMID 36699658, 2022).
growth disorder (1 paper, 2021). "Loss of function of the two other ciliary genes (CEP104 and CROCC) or TSTD2 has not been reported to be associated with a growth disorder, although CROCC has been detected at genome-wide significance for adult height." (PMID 34194391, 2021).
Hypertension (1 paper, 2022). The presence of chronic increased pressure in the systemic arterial system. "This is consistent with the finding of the present study that the TSTD2 antibody levels were strongly associated with hypertension." (PMID 36699658, 2022). "The TSTD2-Ab levels were also found to be higher in males, older adults, smokers, in those who consumed alcohol regularly, and in those with hypertension." (PMID 36699658, 2022).
Stroke (1 paper, 2022). Sudden impairment of blood flow to a part of the brain due to occlusion or rupture of an artery to the brain. "Spearman's correlation analyses to identify the correlations between the TSTD2 antibody levels, and the clinical and demographic variables in the Sawara stroke cohort." (PMID 36699658, 2022).
tumor (1 paper, 2025). "Epas1 might also promote infiltration of tumor-specific T cells into tumors, like Hif1a, since Epas1 controls expression of genes involved in tumor infiltration of immune cells, such as Plk4 and Tstd2." (PMID 39925817, 2025).
TSTD2 also shares sentences with these, for which no sentence is quoted: cerebral infarction (1 paper); Hyperglycemia (1); ischemic stroke (1); kidney disease (1); scoliosis (1); Tall stature (1).